RUNX3 (RUNX family transcription factor 3)
Diseases named in the same sentence as RUNX3 in open-access papers (continued):
Sharing a sentence is not in itself a finding about the gene and the disease.
breast carcinoma (continued). "RUNX3 directly interacts with ERα, and restoration of RUNX3 in MCF-7 breast cancer cells triggers the ubiquitination and degradation of ERα." (PMID 36899853, 2023). "In a more recent study, RUNX3 expression in YAP1-expressing normal mammary epithelial cells, and breast cancer cells, suppressed YAP1-mediated proliferation, migratory capacity and EMT." (PMID 36831308, 2023). "In this study, we found increased RUNX3 expression in exp‐CAF 544 cells and in the stromal fibroblast‐like cells in the cancerous regions in breast cancer patient specimens." (PMID 37641472, 2023). "Cadherin 1 (CDH1), CDKN2A, the runt‐related transcription factor 3 (RUNX3), BRCA1 and RASSF1A are reported to be suppressed by DNMT3B‐dependent DNA hypermethylation in gastric or breast cancers." (PMID 34133843, 2022). "Consistent with the bioinformatics analysis, the expression of RUNX2 was highest in the RUNX family in clinical breast cancer samples and cell lines; Moreover, RUNX2 was overexpressed, while RUNX1 and RUNX3 were decreased in breast cancer tissues." (PMID 35534547, 2022). "Co-expression of RUNX1 or RUNX3 significantly suppressed modulate YAP-mediated oncogenic phenotypes, and inhibited breast cancer progression." (PMID 36092942, 2022). "RUNX1 and RUNX3 preserve against YAP-induced shorter survival outcomes, stemness, and EMT in breast cancer." (PMID 34126594, 2021). "We also analyzed the relationship between the expression levels of RUNX2/RUNX3 and the infiltration of immune cells in BRCA-basal, BRCA-HER2, and BRCA-luminal breast cancer subtypes." (PMID 34485309, 2021). "The genes sharing these GO terms have been previously shown to be involved in breast cancer prognostic process (e.g., CXCR6, KIT, RUNX3) and also immune cell regulation (e.g., CD8B, DAPP1, LY75)." (PMID 33919884, 2021). "We demonstrate a RUNX3-dependent, SE-mediated mechanism for the deregulation of RCAN1.4, which identifies a role for super-enhancers in tumour suppression in breast cancer." (PMID 32771023, 2020). "As RUNX3 was downregulated in breast carcinoma tissues, our findings explored the reason why super-enhancer-driven RCAN1.4 expression was disrupted in breast cancer." (PMID 32771023, 2020). "Similar to RUNX3, the transcription factor GATA3 inhibits breast cancer progression and metastasis by altering the TME." (PMID 31075939, 2019). "RUNX3, a member of the RUNX family of transcription factors, is frequently connected to breast cancer." (PMID 31075939, 2019). "From the study, it is imperative that RUNX3 and RUNX1 regulate YAP-mediated pro-oncogenic phenotypes and YAP-RUNX1-RUNX3 axis has direct implications in breast cancer progression." (PMID 29581836, 2018). "To assess for the clinical significance of RUNX3 and RUNX1 mediated suppression of YAP-mediated oncogenic function, we analyzed available expression dataset of breast cancer patients." (PMID 29581836, 2018). "Extension of this study in breast cancer cell lines, revealed 7 of the YAP-Signature targets that are differentially regulated by RUNX3 in high-YAP compared to that in low-YAP context." (PMID 29581836, 2018). "For instance, in breast cancer, raised levels of PRC2 leads to high levels H3K27 methylation in the promoter regions of FOXC1, E-cadherin, RAD51, RUNX3 and CDKN1C (p57kip2)." (PMID 27845897, 2017). "Among the 340 under-expressed genes containing the 586 hyper-methylated CpGs, there were several tumor suppressor genes with under-expression that has previously been observed in breast cancer, such as L3MBTL4, ID4, RUNX3, PROX1, SFRP1 and others." (PMID 27386846, 2016).
breast carcinoma (continued). "Combined with the findings that RUNX3 is a modulator of ER function and stability, the DEABM assisted in implicating a role for RUNX3 in the generation of ER+ versus ER− breast cancers." (PMID 23704974, 2013). "These included genes/loci previously reported to be methylated in breast cancer (for example SIM1, PAX6, DLX4, RUNX3)." (PMID 20205715, 2010). "LG2 markers include 190 genes, among which are many oncogenes, (BCL2 (down, breast cancer poor prognosis marker), RAD51 (up), EGFR (up), RUNX3 (up), BCL9 (down) and VAV3 (down) and tumor suppressor gene NME1 (up)." (PMID 17683614, 2007). "Our tissue microarray analysis of 241 breast cancer patients indicated that the stromal RUNX3‐positive group had a better outcome of survival than the stromal RUNX3‐negative group." (PMID 37641472, 2023). "Then, we observed significantly more RUNX3‐positive fibroblast‐like cells in cancerous regions than in noncancerous regions in tissue specimens from 10 breast cancer patients." (PMID 37641472, 2023). "In breast cancer, the expression of RUNX2 was higher than that of RUNX1 and RUNX3." (PMID 35534547, 2022). "In contrast, RUNX3 promoter methylation level was significantly higher in breast cancer tissues than normal tissues, regardless of stage, subclass, or histological type." (PMID 34485309, 2021). "In conclusion, all these results suggested that PIM1 could promote breast cancer cells to gain stem cell–like traits and inhibiting PIM1 promised to exert anti‐BrCSC effects with RUNX3 being indispensable in this process." (PMID 32307917, 2020). "And in this paper, we revealed PIM1 to be promising for targeting at to wipe out CSC population specifically due to its regulation on RUNX3 cytoplasmic translocation, and inhibition of PIM1 could attenuate stem cell–like traits of breast cancer cells." (PMID 32307917, 2020). "This is also supported by data from the METABRIC study, where 14% of primary breast cancer samples were found to harbor alterations in CBFB, while 11%, 5% and 4% of patient samples possessed various categories of genetic alterations in RUNX1, RUNX2 and RUNX3, respectively." (PMID 36831308, 2023). "To this end, we knocked down RUNX3 expression in the fibroblasts, grafted them with DCIS breast cancer cells under the skin of highly immunodeficient NOG mice and demonstrated that knockdown of RUNX3 in the exp‐CAFs could suppress the growth of tumors formed with the exp‐CAFs and cancer cells." (PMID 37641472, 2023). "Finally, the dual luciferase reporter assay was used to verify the regulation of RUNX3 on potential target genes ULBP2 and TRDV1, and the effects of ULBP2 and TRDV1 on the growth of breast cancer cells were explored by CCK-8, colony formation and wound healing assays." (PMID 36092942, 2022). "In addition, RUNX1 and RUNX3 may inhibit the YAP-regulated epithelial-mesenchymal transition process and improve breast cancer outcome." (PMID 34485309, 2021). "Interestingly, the invasion capacity of breast cancer cells was also reduced by knocking down PIM1 and the anti‐invasion effect of siPIM1 could also be attenuated by additionally knocking down RUNX3." (PMID 32307917, 2020). "In contrast, RUNX2 mainly exhibits oncogenicroles in breast cancer by promoting invasiveness and metastasis via its target,SNAI2; however it may also play a tumor suppressor role in breast cancer byantagonizing ERα (thus, similar to RUNX3)." (PMID 25415051, 2014). "Interestingly, the vast majority of mutations that result in ER+ tumors in human models produce ER− tumors in mouse models; this is not true of RUNX3+/− mice, which spontaneously develop ER+ mammary tumors." (PMID 23704974, 2013). "However in breast cancer, whether PIM1 acts as an upstream regulator of RUNX3 to phosphorylate it and promote its subcellular dislocation remains unclear and whether this mechanism plays a part in BrCSC‐regulating effect of RUNX3 is hardly referred before." (PMID 32307917, 2020).
colorectal cancer (57 papers, 2007 to 2026). A primary or metastatic malignant neoplasm that affects the colon or rectum. "RUNX3 cytoplasmic retention was already reported by other group to be associated with poor prognosis in colorectal cancer." (PMID 32307917, 2020). "Among the three RUNXs, gene polymorphisms and hypermethylation in RUNX3 have been reported to be related to colorectal cancer." (PMID 28376129, 2017). "Evaluation of the differential expression between carcinoma and normal mucosa showed that SMAD3 rs12708491 and rs2414937, NFκB1 rs230510 and rs3821958, and RUNX3 rs6672420 were associated with several miRNAs for colorectal carcinoma." (PMID 28061442, 2017). "Collectively, these findings provide important insights into the molecular mechanisms of individual MutL homologue tumor suppression and demonstrate an association between TLE mediated antagonism of RUNX3 and accelerated human colorectal cancer progression." (PMID 18551179, 2008). "GC-K significantly inhibits the growth of colorectal cancer cells by inhibiting the DNA expression and activity of methyltransferase 1, inducing demethylation of the RUNX3 promoter in HT-29 human colorectal cancer cells, causing RUNX3 mRNA and protein re-expression and localization in the nucleus." (PMID 36313365, 2022). "Since RUNX3 is a tumor suppressor gene frequently silenced by DNA methylation in colorectal cancer, its reactivation suggests a potential mechanism for vincristine’s anticancer effects." (PMID 41226811, 2025). "Quantitative methylation-specific polymerase chain reaction (QMSP) and real-time PCR analyses confirmed hypermethylation of RUNX3 in a significant proportion of colorectal cancer samples, along with decreased RUNX3 mRNA expression." (PMID 41226811, 2025). "In colorectal cancer, RUNX3 suppresses the stem cell phenotype of colorectal cancer cells by inhibiting Hedgehog signaling." (PMID 38430423, 2024). "Investigations in colorectal cancer confirmed that a decline in RUNX3 expression correlates with increased cell proliferation and invasion." (PMID 38430423, 2024). "For instance, the transcriptional regulation of the tumor suppressor gene RUNX3 is described for colorectal cancer." (PMID 38010391, 2023). "A study reveals that CAF-derived exosomal miR-17-5p promotes an aggressive phenotype in colorectal cancer by initiating a RUNX3/MYC/TGF-β1 positive feedback loop." (PMID 37719863, 2023). "Our results corroborate previous observations that RUNX3 is an important tumor repressor in colorectal cancer." (PMID 36900240, 2023). "Currently, EZH2 and RUNX3 expression are discovered to be dysregulated in colorectal carcinoma tissues or cell strains." (PMID 38048186, 2023). "miR-20a-5p was recently identified as a cancer promoter, which can promote triple-negative breast cancer cells growth via targeting RUNX3 and promote colorectal cancer invasion by downregulating Smad4." (PMID 35351042, 2022). "Additional evidence for this interaction stems from colorectal cancer studies where upregulation of RUNX3 by Bone Morphogenetic Protein (BMP) reduces c-MYC expression, thereby exerting c-MYC tumour-suppressor activity." (PMID 35069677, 2021). "RUNX3 expression has been shown to be lost or downregulated in several tumors, including gastric, breast and colorectal cancers." (PMID 32651460, 2020). "A previous report linked BMP signaling with RUNX3 (a tumor suppressor) in colorectal carcinoma, where the BMP-2 and BMP-4-mediated upregulation of RUNX3 expression inhibited tumor progression." (PMID 32731498, 2020). "Runt-related transcription factor 3 (RUNX3) was validated to be a direct target of miR-301a and downregulating of RUNX3 by miR-301a was demonstrated to promote gastric and colorectal cancer cell proliferation and metastasis is." (PMID 31122259, 2019). "Observing RUNX3 methylation in our data coincides with others who have reported that 21% of colorectal cancer have RUNX3 hypermethylation." (PMID 23505554, 2013).
colorectal cancer (continued). "The aim of this study was to examine the clinical significance of RUNX3 expression in a large series of colorectal cancers using immunohistochemistry and tissue arrays." (PMID 19223906, 2009). "RUNX3/TGF-β1 were also related to the cancer-associated fibroblasts in the tumor microenvironment, which can increase promote tumor progression and lead to poor prognosis in colorectal cancer." (PMID 35522574, 2022). "These outcomes showed that vincristine has an epigenetic effect leading to significant demethylation of RUNX3 in colorectal adenocarcinoma cells that could constitute a novel strategy to treat colorectal cancer." (PMID 34835969, 2021). "In order to examine RUNX3 expression levels and DNA methylation status in colorectal cancer tissues, the use of quantitative methylation-specific polymerase chain reaction (QMSP) analysis and real-time PCR identified hypermethylation of RUNX3 in 70 of 105 colorectal carcinomas (66.7%)." (PMID 34835969, 2021). "Differences in expression between carcinoma and normal mucosa, or differential miRNA expression by genotype, was associated with six SNPs, SMAD3 rs12708492, BMPR2 rs228545, and NFκB1 rs230510, SMAD3 rs2414937, NFκB1 rs3821958, and RUNX3 rs6672420 for colorectal cancer overall." (PMID 28061442, 2017). "Aberrations in RUNX3 have been reported as an early event in colorectal cancer progression." (PMID 25879218, 2015). "Interestingly, another study demonstrated that transcriptional activity of the MYC promoter was down-regulated by up-regulation of RUNX3 in colorectal cancer cells." (PMID 22028816, 2011). "Furthermore, in colorectal cancer tissue, the expression of RUNX3 was disabled, leading to elevated expression of GLI1, activation of Hedgehog signaling and increased ratio of Epcam+CD133+ CSCs, indicating that the RUNX3‐mediated pathway restricts the oncogenic effect of Hedgehog signaling." (PMID 41346572, 2025). "In addition, RUNX3 mRNA expression decreased in 68 of 105 colorectal cancer tissues (64.8%)." (PMID 34835969, 2021). "Our study of human colorectal cancer tissue microarray (TMA) also revealed positive and statistically significant correlations between the expressions of RUNX1, RUNX2, and RUNX3 in both CD8+T cells and CD103+CD8+T cells." (PMID 39822248, 2024). "RUNX3 was earlier shown to promote ubiquitination of MYCN in neuroblastoma and the Hedgehog pathway oncogenic transcription factor GLI1 in colorectal cancer cells." (PMID 37400551, 2023). "Knowing that RUNX3 represses TBC1D7, our observation appears to pinpoint RUNX3 to reciprocal control of the Wnt/β-catenin and PI3K/AKT/mTORC1 pathways, inter alia involved in the failure of colorectal cancer treatment." (PMID 37371794, 2023). "miR-19a-3p also reported to be involved in the proliferation of colorectal cancer by targeting TIA1 and regulates progression of glioma by targeting RUNX3 directly." (PMID 33014522, 2020). "We obtained 401 colorectal cancer specimens and successfully quantified DNA methylation in eight CIMP-specific gene promoters (CACNA1G, CDKN2A, CRABP1, IGF2, MLH1, NEUROG1, RUNX3, and SOCS1) using MethyLight technology." (PMID 31690257, 2019). "In the distal colorectal cancer network, two biomarkers were hubs including NEUROG1 methylation (degree centrality = 0.15) and RUNX3 methylation (degree centrality = 0.15)." (PMID 28623901, 2017). "The Laird methylation marker panel used to determine CIMP status of colorectal cancers consists of the CACNA1G, IGF2, NEUROG1, RUNX3 and SOCS1 genes." (PMID 20846368, 2010). "TLE6D is recurrently overexpressed in human colorectal cancers and TLE6D expression correlates with RUNX3 expression." (PMID 18551179, 2008).
colorectal cancer (continued). "We obtained 920 colorectal cancer specimens and quantified DNA methylation in the 8 CIMP-specific gene promoters (CACNA1G, CDKN2A, CRABP1, IGF2, MLH1, NEUROG1, RUNX3 and SOCS1) by MethyLight technology." (PMID 17474983, 2007). "The treatment with this alkaloid induced the demethylation of RUNX3, leading to the recovery of RUNX3 mRNA expression in colorectal cancer cells without affecting DNA methylation in healthy colon cells." (PMID 36498571, 2022). "Our previous studies had confirmed that downregulation of RUNX3 expression was closely related to the occurrence and development of colorectal cancer, whereas the specific mechanisms were not reported in detail." (PMID 32184893, 2020). "Finally, it is worth pointing out that CELF4, TCF7L2, FTO, RUNX1, RUNX3, and CTNNB1 have all been reported to be involved in the etiology of colorectal cancer." (PMID 23626757, 2013). "However, the mechanism of RUNX3-mediated suppression of cancer metastasis remains unclear and the role of RUNX3 in colorectal cancer has not yet been well studied." (PMID 32765634, 2020). "Another important clinical study demonstrated hypermethylation of RUNX family transcription factor 3 (RUNX3) in the serum samples of gastric, non-small cell lung cancer (NSCLC), and pancreatic, liver, and colorectal cancers, whereas no methylation was detected in healthy samples." (PMID 36765652, 2023). "Utilizing MethyLight technology (real-time PCR), we quantified DNA methylation in 8 CIMP-specific promoters {CACNA1G, CDKN2A (p16), CRABP1, IGF2, MLH1, NEUROG1, RUNX3 and SOCS1} in 758 non-MSI-high colorectal cancers obtained from two large prospective cohorts." (PMID 17474983, 2007).